IL6 (interleukin 6)
Diseases named in the same sentence as IL6 in open-access papers (continued):
Sharing a sentence is not in itself a finding about the gene and the disease.
Sepsis (continued). "In recent years, great progress has been made in searching for biomarkers of sepsis, including CALCA (also known as PCT), C-reactive protein, and interleukin-6 which have been found to be biomarkers of sepsis." (PMID 32596378, 2020). "In higher degree burns, IL-6-induced levels of circulating CRP elevate, and in sepsis, it increases to 100,000 pg/mL." (PMID 31979357, 2020). "The combination of IL-6 and CRP has recently been shown to be useful in the early diagnosis of sepsis in newborns." (PMID 33233806, 2020). "Significant differences were observed in the expression of the pro-inflammatory cytokine genes IL-2, IL-6, TNF, and IFN-γ and the anti-inflammatory cytokine genes IL-4 and IL-10 between sepsis patients and healthy controls." (PMID 32922168, 2020). "Serum cytokines, including IL-6, IFN-γ, TNF-α, and IL-10, were elevated in the control groups and in SnPP-treated rats indicating sepsis." (PMID 32015027, 2020). "As SOCS3 can inhibit the IL-6/STAT3 pathway, ADAR1 is expected to reduce IL-6 levels by regulating the expression of SOCS3, thereby inhibiting inflammation and alleviating sepsis." (PMID 32273831, 2020). "When survivors of the two groups were compared, the levels of serum IL-2R, IL-6, IL-8, and TNF-α were lower in SARS-CoV-2 sepsis survivors." (PMID 33329592, 2020). "Patients with sepsis were significantly younger and had significantly higher plasma concentrations of the inflammatory markers PCT, CRP, NGAL and IL‐6 at ICU admission and a significantly longer duration of hospital stay than patients with CAP." (PMID 32916773, 2020). "Infectious complications and sepsis enhance the proinflammatory cytokine cascade, including TNF-α, IL-1, IL-6, and IL-8." (PMID 33643891, 2020). "We reviewed six promising biomarkers for detecting sepsis and systemic infection, including C-reactive protein (CRP), procalcitonin (PCT), interleukin-6 (IL-6), CD64, presepsin, and sTREM-1." (PMID 33198109, 2020). "The presented LFAs were designed to detect the sepsis biomarkers CRP and IL-6 simultaneously on one test line, by using two different QDs as labels." (PMID 32912236, 2020). "Plasma IL-6 and TNF-α levels were markedly high in the patient with sepsis, as compared to those in the other cardiogenic post-CA patients." (PMID 33041520, 2020). "Analytical investigations showed not only that copeptin levels were significantly higher in sepsis cases compared to non-sepsis ones (p < 0.001), but also that they correlated with PCT, CRP, and IL-6 blood levels." (PMID 33092081, 2020). "In fact, this has been implied in our previous work that demonstrated plasma EVs isolated from sepsis mice promoted significant CXCL2 and IL-6 via miRNA- and TLR7-dependent mechanisms." (PMID 32958516, 2020). "A cytokine array found that the QX1 formula attenuated sepsis-induced upregulated levels of serum IFN-γ, IL-1β, IL-3, IL-6, IL-17, IL-4, IL-10, and TNF-α." (PMID 32908632, 2020). "Further inflammatory mediators involved in sepsis pathogenesis are the pro-inflammatory cytokines tumor necrosis factor-α (TNF-α), interferon-γ (IFN-γ), and the interleukins IL-1β and IL-6." (PMID 32948040, 2020). "This is further reinforced by the fact that the M1 cytokines, IL1, IL‐6 and TNF are consistently increased in the hippocampus late after sepsis, and IL‐10 has some peaks during sepsis evolution and CCL‐22 is not increased at all." (PMID 31654493, 2020). "The levels of pro-inflammatory cytokines, including tumor necrosis factor (TNF)-α, IL-1β, IL-6, and MCP-1, have been observed to increase in the myocardium in response to sepsis." (PMID 32256344, 2020). "In a rat model of endotoxin induced sepsis, pretreatment with capsaicin increases anti-inflammatory cytokine IL-10 levels, and attenuation of CGRP, TNF, and interleukin 6 (IL-6) cytokines." (PMID 33193423, 2020). "This was correlated with decreased IL-6 levels in the peritoneum of mice with cecal ligation and puncture (CLP)-induced polymicrobial sepsis." (PMID 32849612, 2020).
Sepsis (continued). "Several clinical studies have identified distinct patterns of elevated circulating cytokines in patients with sepsis and septic shock, and our finding of increased plasma TNF-α and IL-6 levels in the mouse model is consistent with these clinical data." (PMID 31959927, 2020). "For this purpose, we used antagomir-21 to inhibit miR-21 expression in murine sepsis model and detected the levels of proinflammatory cytokines (TNF-α, IL-1β, and IL-6), liver injury markers (AST, ALT), and PPARα expression." (PMID 33424957, 2020). "The median levels of IL-6, PCT, and CRP were statistically significantly higher in children with sepsis compared to children with SIRS (118 pg/ml, 2.55 ng/ml, and 48 mg/l vs. 52 pg/ml, 1.0 ng/ml, and 33.5 mg/l, respectively)." (PMID 32655314, 2020). "Specifically, IL-6, IL-8, KC-like, and RANTES were the biomarkers that were most discriminating for sepsis in cats." (PMID 32548135, 2020). "Serial monitoring of serum CRP, PCT, IL-6, IL-1b, sIL-2R, and LBP after death has been suggested to be helpful for the postmortem diagnosis of sepsis, but more studies are needed." (PMID 31661804, 2019). "Multivariate logistic regression was performed to model the ability of the biomarker combination (IL-6 and PTX3) to discriminate septic shock patients from sepsis and to predict 28-day mortality among the overall patients." (PMID 31718563, 2019). "In myocardium, TNF and IL-6 were significantly elevated in sepsis, TNF in both ventricles and IL-6 mostly in RV, while IL-1β, IL-18 and C5a were significantly higher in RV compared to LV after PAB (all p<0.05)." (PMID 31247004, 2019). "Expression of IL6, ICAM1, and VCAM1 were significantly upregulated following treatment of the HMECs with LPS for 24 h confirming induction of sepsis." (PMID 31231228, 2019). "Inhibition of calcium/calmodulin-dependent protein kinase Iα increased survival rate by reducing systemic concentrations of IL-10, IL-6, TNF-α, and HMGB1 in a CLP model of sepsis." (PMID 30848296, 2019). "More than 170 biomarkers have been identified for the assessment of sepsis, including PCT, CRP, TNF-α/IL-6, MCP-1, miRNA, and other indicators." (PMID 31671729, 2019). "LPS-induced sepsis is less severe when injection at ZT10 than at ZT12, coinciding with a decrease in pro-inflammatory cytokines TNF-α, IL-6, and CXCL1 at ZT12, and increase in the anti-inflammatory cytokine IL-10." (PMID 31470863, 2019). "IL-6 plays a vital role in acute renal damage, which is regarded to be a predictor of AKI in patients with serious sepsis." (PMID 31234591, 2019). "Patients in the higher IL-6 groups had significantly higher proportions of septic AKI, and lower proportions of cardiovascular disease induced AKI (low vs. middle vs. high; sepsis, P < 0.0001; cardiovascular disease, P < 0.0001)." (PMID 30823904, 2019). "Chronic inflammation may lead to several inflammatory disorders including sepsis, rheumatoid arthritis, asthma, diabetes and Crohn’s disease and involves production and secretion of various pro-inflammatory cytokines including IL6, TNF and high mobility group box-1 (HMGB1)." (PMID 30947238, 2019). "The α7 nAChR partial agonist GTS-21 reduces secretion of pro-inflammatory cytokines including interleukin-6 (IL6) and tumor-necrosis factor (TNF) in models of endotoxemia and sepsis, and its anti-inflammatory effects are widely ascribed to α7 nAChR activation." (PMID 30947238, 2019). "Despite resolution of bacteremia, plasma IL-6 concentration was elevated at day 4 (p<0.0001), but comparable to NSC by 2 weeks in both male and female sepsis survivors (p=0.999 and p=0.667, respectively)." (PMID 31793435, 2019). "Our results were further validated in an in vivo model of sub-lethal LPS-induced sepsis, whereby siRNA mediated knockdown of UCA1 and HULC lncRNAs prevented induction of VCAM1, ICAM1, and IL6, as assayed by immunohistochemistry." (PMID 31231228, 2019).
Sepsis (continued). "Specific biomarkers that have recently shown promise in prognosticating human sepsis include serum procalcitonin (PCT), N-terminal brain natriuretic propeptide (NT-proBNP), interleukin-6 (IL-6), prothrombin time (PT), and thrombin time (TT)." (PMID 30931316, 2019). "Patients with sepsis showed significant decreases in hemoglobin, plasma iron and sTfR/log ferritin and significant increases in plasma EPO, sTfR, hepcidin, ferritin and IL-6 on days 1, 3 and 7 of ICU admission compared with healthy volunteers." (PMID 31183575, 2019). "Currently, IL-6, CRP and PCT are the most commonly used biomarkers of sepsis, which severity and outcome prediction capacity is of high clinical research interest." (PMID 31781117, 2019). "During inflammation and sepsis, plasma C-reactive protein (CRP), IL-6, IL-1β, and TNF-α levels in the circulatory system are increased." (PMID 31835381, 2019). "Overall, our study shows that there is an “immunoparalysis” in severe leptospirosis and sepsis: low quantity of NK and TCD4+ cells, low expression of IFN-γ, IL-12, IL-6, IL-1 and IL-2 and high expression of IL-10." (PMID 31114579, 2019). "Myocardial mRNA levels of IL-1β, IL-6, IL-18, IP-10, E-selectin and PAI-1 were significantly elevated in RV and LV during sepsis compared to PAB, while Caspase-1 was decreased in septic compared to PAB animals (all p<0.05)." (PMID 31247004, 2019). "Patients in the early stages of sepsis showed higher concentrations of TNF, IL-1β, and IL-6 than healthy controls and they had an elevated activation of the proinflammatory transcription factor NFκB in blood leukocytes." (PMID 31072006, 2019). "Sepsis severity was evaluated by murine sepsis scores, blood bacterial load, plasma tumor necrosis factor-α [TNF-α]/interleukin-6 [IL-6] levels and histopathology of vital organs." (PMID 31501504, 2019). "Serum levels of IL-6, PTX3, and PCT were measured in 142 enrolled subjects (51 with sepsis, 46 with septic shock, and 45 as controls)." (PMID 31718563, 2019). "Other evidence has indicated that miR-23b plays crucial roles in the pathomechanism of sepsis by suppressing the production of inflammatory cytokines, including NF-κB, TNF-α, IL-6, IL-1β, and E-selectin." (PMID 31780861, 2019). "Serum cytokines, including IL6, IFNγ, IL1β, IL10, and TNFα were high suggesting the onset of sepsis in most of these mice even though there was a high degree of variation of bacterial load." (PMID 31121001, 2019). "The aim of the present study was to evaluate the dynamics of IL-6, PCT and CRP in a large population of adult patients with sepsis regarding their timely prediction of success of antibiotic therapy and survival." (PMID 30760225, 2019). "Post-treatment IL-6 and TNF plasma levels were decreased, suggesting an interesting strategy for sepsis." (PMID 31114571, 2019). "Similar to the findings at 48 hpi, the majority of both WT and Myd88−/− mice had very high levels of IL-6, TNF-α, and IL-10, indicative of progressing sepsis." (PMID 30642901, 2019). "Biomarkers play an important role in the early diagnosis of sepsis, the judgement of condition and prognosis, and the evaluation of curative effect, such as the detection of procalcitonin (PCT), interleukin-6 (IL-6), and white blood count (WBC)." (PMID 31915467, 2019). "In the present study, we observed that FX can significantly inhibit the production of inflammatory cytokines IL-6, IL-1β, and TNF-α and promote the sepsis mouse model survival rate from 0% to 40% for the first time." (PMID 31555126, 2019). "In order to further investigate the effects of miR-106a on sepsis, we selected three cellular inflammatory factors TNF-α, IL-1β, IL-6 as representatives for research." (PMID 31432993, 2019). "The levels of copeptin were found to be significantly higher in sepsis cases, and the concentrations correlated with PCT, CRP, and IL-6 values." (PMID 31661804, 2019).
Sepsis (continued). "High levels of circulating pro-inflammatory cytokines, such as TNFα, IL-1, and interleukin-6 (IL-6), were cited as evidence of SIRS in both septic human patients and laboratory animals with induced sepsis." (PMID 30931316, 2019). "Comparison of molecules between the control and sepsis groups revealed statistically significant differences, except for IFN-α, IL-1RA, IL-1β, IL-2, IL-6, IL-7, IL-15, LIF, GM-CSF, TNF-α, CCL4, CCL5, and CXCL12." (PMID 31583025, 2019). "GTS-21 (also known as DMBX-anabaseine) inhibits pro-inflammatory cytokines like TNF, IL-1β, IL6 and HMGB1 and improves survival in murine endotoxemia and sepsis models." (PMID 30947238, 2019). "An older study on 16 patients with sepsis-related multiple organ failure using an intermittent high permeability hemofiltration over five days for 12 h per day alternated with conventional hemofiltration showed that IL-6 could be eliminated effectively by high cut-off membranes." (PMID 31026303, 2019). "Administration of 3-methyladenine (3-MA) (an autophagy inhibitor) attenuated the sepsis symptoms as well as the IL-6 and TNF-α production in a lethal model of murine sepsis." (PMID 31892110, 2019). "We found that the mRNA expressions of TNF-α, IL-1β, and IL-6 were upregulated in MLN DCs and those of IL-1β and IL-6 were augmented in SP DCs by sepsis." (PMID 31323786, 2019). "The levels of leptin seem to rapidly increase in acute inflammatory conditions, such as cholecystectomy and sepsis, particularly favored by cytokines such as TNF-α, IL-6, and IL-1β." (PMID 30949073, 2019). "We tried to use Sepsis-3 criteria to study the diagnostic value of volume, conductivity, and scattering (VCS) parameters in sepsis and infection in patients with liver cirrhosis compared with traditional infection markers (PCT, IL-6, sCDl63)." (PMID 31915467, 2019). "In severely burned patients with sepsis, plasma levels of endotoxin and cytokines, including TNF-α, IL-1β, IL-6, and IL-8 after CRRT were significantly reduced based on those before the therapy." (PMID 29649247, 2018). "The concentrations of IL-6 (100.45 ± 21.06 pg/mL), PCT (5.38 ± 0.58 ng/mL) and CRP (51.65 ± 6.25 ng/mL) were also higher in sepsis patients group." (PMID 30587127, 2018). "Circulating levels of the cytokines IL-6, IL-8, IL-10, MCP-1, IP-10, and TNF were significantly increased in septic patient at all three time points (<12 hours, 4 days, and 14 days after sepsis) compared to healthy controls." (PMID 30300408, 2018). "Several studies have confirmed that presepsin is a more specific and sensitive marker for the diagnosis of sepsis compared with C-reactive protein (CRP), interleukin-6 (IL-6), or procalcitonin (PCT)." (PMID 30470216, 2018). "All 134 sepsis patients were followed for DcR3, PCT, CRP, and IL-6 levels during the whole course of hospitalization." (PMID 29541387, 2018). "CLP-sepsis in mice on HFD resulted in large increases in the serum levels of TNF-α, IL-6, KC, and IL-10 when compared to mice on HFD subjected to sham surgery and mice on chow diet subjected to CLP (P < 0.05)." (PMID 30619349, 2018). "In particular, male patients display higher levels of pro-inflammatory cytokines such as IL-6 and TNF-α as well as increased levels of bacteremia markers like procalcitonin in sepsis than females." (PMID 29925409, 2018). "In all patients with sepsis, serum tenascin-C was significantly positively correlated with SOFA score (P = 0.011), serum creatinine (P = 0.006), CRP (P = 0.001), IL-6 (P < 0.001) and TNF-α (P = 0.026)." (PMID 30442110, 2018). "Plasma cytokine levels of IL-1β, TNF-α, IL-6, and MCP-1 were markedly increased in patients with sepsis compared to those in healthy control subjects." (PMID 30337925, 2018). "Our study showed that serum levels of tenascin-C in patients with sepsis were significantly positively correlated with serum inflammatory factors, CRP, IL-6 and TNF-α." (PMID 30442110, 2018).
Sepsis (continued). "As a predictor of the persistence/development of severe sepsis on the third day of observation (n = 46), the highest AUC was shown for PCT, followed by sTREM-1, IL-6 and CRP." (PMID 29282483, 2018). "Thereby, it was an earlier indicator for inflammation than the increase of the pro-inflammatory cytokines IL-6 and TNF-α, which reached statistical significance two hours after induction of sepsis." (PMID 30060473, 2018). "Hendriks demonstrated that peritoneal cytokine levels (especially IL-6, TNF-α, and IL-10) were dramatically different in rats who either survived or succumbed to an intra-peritoneal sepsis model in the 24 h after cytokine determination." (PMID 29977328, 2018). "Serum concentration of IL-6 at discharge, time after ICU discharge, time between sepsis diagnosis and antibiotic administration, cumulative dose of haloperidol and mean levels of blood glucose during ICU stay affected the performance of these patients on MMSE." (PMID 29540719, 2018). "A PLR of 9.94 suggests that neonates with sepsis and PROM have a 9.94-fold higher chance of being IL-6-positive than neonates with PROM." (PMID 30461611, 2018). "Then, we detected the expression levels of IL-1β, IL-6 and TNF-α in patients with sepsis and healthy subjects to evaluate the influence of the functional IL-27 SNP on the production of these related cytokines." (PMID 30268141, 2018). "The most commonly used biomarkers for sepsis are procalcitonin (PCT), C reaction protein (CRP) and interleukin 6 (IL-6)." (PMID 29541387, 2018). "Our data, for the first time, demonstrated that pilloin reduces IL-6 and TNF-α levels in an LPS-induced sepsis model." (PMID 30513815, 2018). "Only the levels of IL-6 and TNF-α were decreased in the AKI with sepsis group (P = 0.046 and P = 0.008, respectively)." (PMID 30666251, 2018). "Previous in vivo and in vitro studies have demonstrated that HO-1 reduces the production of proinflammatory cytokines, including TNF-α and IL-6, and inhibits the activation of NF-κB and MAPK signaling during sepsis." (PMID 30533176, 2018). "Cytokine changes have been extensively studied in patients with septicemia or after exposure to endotoxin with sequential increases in TNF-α, IL-1β, IL-6, IL-1Ra, and IL-10." (PMID 29149303, 2018). "In contrast to these in vitro results, data from experimental sepsis in rats suggest that both pro-inflammatory (TNF, IL-6) and anti-inflammatory (IL-10) mediators were increased by HCl infusion." (PMID 29589205, 2018). "Ghrelin suppressed the release of IL-6 and TNF-α in the peritoneal cavity and the lungs in a sepsis model and in the brain in a focal cerebral ischaemia model in rats through a mechanism that requires intact vagus nerves." (PMID 29593559, 2018). "In previous studies on HMGB1, TNF-α and IL-6 were often used for reference and comparison with HMGB1, especially in studies on sepsis." (PMID 30157804, 2018). "Considering these findings and the importance of the early assessment of the clinical course of sepsis, the prognostic value of sTREM-1 compared with CRP, PCT and IL-6 was analyzed in the present study." (PMID 29282483, 2018). "Lipopolysaccharide (LPS) and sepsis-related inflammatory factors such as TNF-α and IL-6 can regulate the secretion of PCT." (PMID 30595763, 2018). "All these studies show that both type-1 and type-2 diabetic animals have exacerbated hyperglycemia, and production of both pro- (TNF, IL1, IL6, MCP1) and anti-inflammatory (IL10) cytokines in experimental sepsis." (PMID 29780390, 2018). "Regression analyses demonstrated significant, inverse correlations between IL-6, IL-10, and MCP-1 levels and days after sepsis." (PMID 30300408, 2018). "Network analysis revealed a network formed by PAI-1, IL-6, IL-8, MCP-1 and IL-10 on days 1, 2 and 4 throughout the acute phase of sepsis." (PMID 30228372, 2018).